MMP3 (matrix metallopeptidase 3)
Diseases named in the same sentence as MMP3 in open-access papers (continued):
Sharing a sentence is not in itself a finding about the gene and the disease.
osteosarcoma (continued). "In conclusion, we have shown that glucosamine sulfate exerts a pronounced suppressive effect on MMPs in osteosarcoma cell lines in vitro; this effect was most pronounced for MMP-3 and MMP-9 to a lesser extent." (PMID 27562075, 2016). "Herein, we report, for the first time, that glucosamine sulfate exerts a pronounced suppressive effect on MMPs, particularly on MMP-3 and -9 in osteosarcoma cell lines in vitro." (PMID 27562075, 2016). "In the present study, we demonstrate that a relatively low concentration of 10 μg/ml glucosamine sulfate reduces MMP-3 expression more than 50 % in both of the osteosarcoma cell lines investigated." (PMID 27562075, 2016). "Results indicated CTGF inducing upregulation of MMP-2 and MMP-3 expression in human osteosarcoma cells by down-regulating miR-519d through MEK and ERK pathway and contributing the tumor metastasis." (PMID 25003330, 2014). "Expression of CTGF, MMP-2, and MMP-3 in osteosarcoma patients was significantly higher than in normal bone." (PMID 25003330, 2014). "This study characterized effect of CTGF on production of MMP-2 and MMP-3 in human osteosarcoma, which is responsible for subsequent increased migration and metastasis." (PMID 25003330, 2014). "Knockdown of MMP-2 or MMP-3 expression via transfection with MMP-2 or MMP-3 siRNA abolished CTGF-induced osteosarcoma cell migration activity, meaning both MMP-2 and MMP-3 involved in CTGF-mediated cell migration." (PMID 25003330, 2014). "Indeed, combining itraconazole and MMP3 inhibitor VII additively suppressed the proliferation of osteosarcoma cell lines." (PMID 38622340, 2024). "One study demonstrated that knocking down UBCH10 in osteosarcoma cell lines resulted in the downregulation of Ki-67, MMP-3 (matrix metalloproteinase-3), and MMP-9 (matrix metalloproteinase-9), leading to decreased proliferation, invasion, and migration capabilities of OS cells." (PMID 39062505, 2024). "The correlation between CCL2 and MMP-3 was found to be positive in osteosarcoma." (PMID 37893141, 2023). "We indicated that CCL2 promotes MMP-3-mediated migration of osteosarcoma." (PMID 37893141, 2023). "Therefore, miR-3659 plays a crucial role in CCL2-induced osteosarcoma cell motility by regulating MMP-3 expression." (PMID 37893141, 2023). "The inhibition of MMP-3 decreases osteosarcoma cell migration and invasion." (PMID 37893141, 2023). "Thus, our findings suggest that MMP-3 is indeed involved in CCL2-induced osteosarcoma cell migration and invasion." (PMID 37893141, 2023). "Subsequently, we conducted IHC staining to observe MMP-3 levels in osteosarcoma patients." (PMID 37893141, 2023). "Therefore, combined C1GALT1 and MMP3 inhibition could be an even more effective candidate therapy for osteosarcoma." (PMID 38622340, 2024). "Therefore, CCL2 and MMP-3 are highly expressed in metastatic osteosarcoma in vivo." (PMID 37893141, 2023). "The in vivo lung metastatic osteosarcoma model also demonstrated similar effects, showing higher levels of CCL2 and MMP-3 in lung metastatic osteosarcoma tissues." (PMID 37893141, 2023). "The stimulation of osteosarcoma cells with CCL2 enhanced migration and invasion abilities through the upregulation of MMP-3 synthesis." (PMID 37893141, 2023). "The migration and invasion properties of MMP-3 knockdown, MG-63 and TE85 highly metastatic osteosarcoma cells were extraordinarily deteriorated." (PMID 32377334, 2020). "To identify the mediator of MCP-1-promoted osteosarcoma migration, we further examined the expression of MMP-1, MMP-2, MMP-3, MMP-7, MMP-9, MMP-12, and MMP-13 mRNA under MCP-1 stimulation." (PMID 33228783, 2020). "To identify the mediator of TSP‐2‐promoted osteosarcoma migration, we examined levels of MMP‐1, MMP‐2, MMP‐3, MMP‐7, MMP‐9, MMP‐12 and MMP‐13 mRNA expression following TSP‐2 stimulation." (PMID 33021341, 2020). "The malignant phenotype in osteosarcoma cells is obviously promoted by another metalloproteinase, the MMP-3 (also known as stromelysin-1)." (PMID 32377334, 2020).
osteosarcoma (continued). "Studies have revealed that MMPs such as MMP-2, MMP-3, and MMP-9 are involved in osteosarcoma progression and metastasis." (PMID 33228783, 2020). "Studies have revealed that MMPs including MMP-1, MMP-2, MMP-3, MMP-7, MMP-9, MMP-12, and MMP-13 are significantly related to osteosarcoma metastasis and poor prognosis." (PMID 33228783, 2020). "In this study, we found a pronounced suppressive effect of glucosamine sulfate particularly on MMP-3 and also MMP-9 mRNA and protein levels in osteosarcoma cell lines in vitro." (PMID 27562075, 2016). "Additionally, the downregulation of MMP-3 and MMP-13 can decrease osteosarcoma cell migration and invasion." (PMID 37893141, 2023). "In the present study, it was shown that expression of MMP3 is elevated in canine osteosarcoma in comparison to non-malignant bone tissue." (PMID 32854182, 2020). "Connective tissue growth factor (CTGF) could promote osteosarcoma cells metastasis through the elevation of MMP-2 and MMP-3." (PMID 28938584, 2017). "Quantitative RT-PCR analysis of CTGF, MMP2, MMP-3, and miR-519d performed in osteosarcoma and normal samples, showed negative correlation between CTGF and miR-519d; positive correlation between CTGF and MMP-2, CTGF and MMP-3." (PMID 25003330, 2014). "However, it is not clear which miRNA regulates MMP3 in CCL2-induced osteosarcoma cell motility." (PMID 37893141, 2023).
coronary artery disease (16 papers, 2004 to 2024). "Conclusions on susceptibility of MMP3-1612 5A/6A to morbid risk of coronary artery disease (CAD) are controversial." (PMID 38084252, 2023). "In contrast, the reduced activity of MMP-3 in 6A/6A individuals with coronary heart disease contributed to the increased risk of restenosis, perhaps because of the failure of connective tissue remodeling." (PMID 23108733, 2013). "Polymorphisms in genes associated with the regulation of calcium levels (CASR, CYP24A1, CARS, DGKD, DGKH/KIAA0564 and GATA3) and metalloproteinases (MMP-3 and MMP-9) were also associated with an increased risk of coronary artery disease and AMI." (PMID 38478535, 2024). "Regarding MMP-3, studies have found a direct association between MMP-3 and coronary artery disease, subsequent complications, and clinical outcomes." (PMID 40143911, 2024). "Serum MMP-3 level was higher in patients with aneurismal coronary artery disease compared to the control group (20.23 ± 14.68 vs 11.45 ± 6.55 ng/ml, p = 0.039)." (PMID 15482602, 2004). "We investigated the association between MMPs and coronary artery aneurysm by measuring the levels of MMP-1 and MMP-3 (both of which represent markers of proteolytic activity) in patients with coronary artery disease, some of whom had coronary aneurysms (cases) and others who did not (controls)." (PMID 15482602, 2004). "As one of the highest incidences of CVDs, coronary artery disease links with more than 20 targets in this T-cD network, such as VCAM1 and ICAM1 (reported to increase in dysfunctional endothelial cells), MMP9, MMP3, and MMP2 (being influencing factors in cardiac fibrosis)." (PMID 29861771, 2018).
breast tumors (15 papers, 2006 to 2024). "MMP-3 expression was associated with benign and early stage breast tumours but is frequently lost in advanced stage, aggressive breast disease." (PMID 19243594, 2009). "MMP-1 (interstitial collagenase) has been associated with MDA-MB-231 invasion in vitro, while MMP-3 (stromelysin-1) has been localised around invasive cells of breast tumours in vivo." (PMID 16430785, 2006). "RAC1B facilitates EMT progression following matrix metalloproteinase 3 (MMP-3) expression in breast tumors by increasing ROS that induce the expression of EMT transcription factor Snail." (PMID 39001533, 2024). "We also determined that MMP-1 and MMP-3 mRNA levels were higher in all types of breast tumors than in normal breast tissue." (PMID 31534541, 2019). "MMP3 has been suggested to have a role in modulating chemotherapeutic response in head and neck cancers and has been shown to play a role in breast tumour carcinogenesis." (PMID 19832977, 2009). "MMP-3 is expressed in areas of tissue growth, focally expressed around invasive cells in the stromal component of breast tumours, and expressed in both benign and malignant breast phenotypes." (PMID 16430785, 2006). "MMP-3 was the most expressed MMP in ductal breast tumor cells (mean IOD value 22,300)." (PMID 27975070, 2016). "IHC and ISH in vivo analysis has demonstrated MMP-3 in both the tumour and stroma cellular compartments of both invasive and non-invasive tumours, with the level of stromal expression increasing with tumourigenicity, and in the extracellular matrix adjacent to breast tumours." (PMID 16430785, 2006). "Pelisch and colleagues investigated the molecular mechanisms by which stromelysin-1/matrix metalloproteinase-3 (MMP3), a stromal enzyme upregulated in many breast tumors and other stroma-rich cancers, leads to induction of RAC1B expression." (PMID 30621237, 2019). "IL-17-dependent invasion of breast tumours was blocked by a range of selective MMP antagonists for MMP-2, MMP-3 and MMP-9 as well as a broad-spectrum MMP antagonist." (PMID 19014637, 2008). "Moreover, a few genes involved in modulation of the extracellular matrix (ADAMTS4, MMP1, MMP3, and angiogenesis (MFAP5, SFRP2, SRPK1, VEGF, and CHI3L1) were found to be expressed at higher levels in the primary breast tumors compared with the bone metastases." (PMID 23174366, 2012).
glioblastoma (15 papers, 2016 to 2025). The most malignant astrocytic tumor (WHO grade IV). "GBP5 promotes glioblastoma matrix degradation via Src/ERK1/2/MMP3, aiding vascular co-option and metastatic progression, linked to its Golgi-based signaling and immune modulation." (PMID 40564939, 2025). "Further in vivo studies had shown that glycitein affected glioblastoma cells by reducing the activity of matrix metalloproteinase-3 (MMP-3), nuclear transcription factor (NF-κB), and AP-1." (PMID 40941056, 2025). "Expression of several MMPs, including MMP-1, -2, -7, and -9, correlates with tumor grade, whereas MMP-3 appears to play a limited role in glioblastoma progression." (PMID 41515435, 2025). "The induction of expression of MMP3 in glioblastoma cells triggers a cascade of gene expression events, resulting in decreased cell adhesion and migration." (PMID 38879494, 2024). "The induction of expression of MMP3 in glioblastoma cells triggers a cascade of gene expression, resulting in decreased cell adhesion and migration." (PMID 36959545, 2023). "In particular, MMP-3 has been reported that is involved in the cellular migration in glioblastoma cells, VSMCs, and adult neural progenitor cells." (PMID 34019587, 2021). "MMP-3 is involved in cell migration in various types of cells, including glioblastoma, vascular smooth muscle, and adult neural progenitor cells." (PMID 34019587, 2021). "Previously, we demonstrated an increased expression of MMP-3 mRNA in response to C/EBPδ activation in glioblastoma-astrocytoma U373MG cells." (PMID 26510742, 2016). "Our previous micro-array data showed that C/EBPδ upregulates MMP-3 expression in human glioblastoma-astrocytoma U373MG cells." (PMID 26510742, 2016). "The small molecules from T. versicolor (SMCV) not only have indirect anti-cancer effects by inhibiting TNF-α-induced MMP-3 production in glioblastoma T98G cells but also directly reduce the invasive ability of malignant cells such as T98G, A549, and MDA-MB-231 cells." (PMID 40507156, 2025). "GBP5 supports positive outcomes in endometrial, ovarian, and colorectal cancers, often through immune infiltration, but accelerates malignancy in stomach cancer via a JAK1-STAT1/GBP5/CXCL8 positive feedback loop and in glioblastoma via Src/ERK1/2/MMP3 signaling." (PMID 40564939, 2025). "An increase in the protein levels of MMP1, MMP2, MMP3, and MMP8 was observed in astrocytoma samples, while a reverse trend was noted, with a decrease in the amount of these proteins in the glioblastoma group when compared to the control group." (PMID 38474106, 2024). "Even when correlating glioblastomas versus astrocytomas, we showed a significantly increased level of MMP1, MMP3, MMP13, and TIMP1." (PMID 38474106, 2024). "An elevation in the protein levels of MMP1, MMP2, MMP3, and MMP8 was observed in astrocytoma samples, whereas a decrease in the amount of these proteins was noted in the glioblastoma group compared to the control group." (PMID 38474106, 2024). "Overall, changes in fold regulation with statistical significance were recorded for MMP3 (p < 0.001), MMP10 (p < 0.001), and TIMP2 (p < 0.05) in glioblastoma." (PMID 38474106, 2024). "Additionally, guanylate-binding protein 5 (GBP5) promotes glioblastoma malignancy through the SRC/ERK1/2/MMP3 pathway, implicating ETS1 and MMP3 as downstream effectors of SRC signaling." (PMID 41462902, 2025). "In addition, the activity of matrixmetalloproteinases MMP2, 9, and 3 play a pivotal role in this scenario: if agrin is cleaved by MMP3 —such as in glioblastoma—no typical OAPs are found and if MMP2 and 9 cleave dystroglycan —such as in glioblastoma—no OAPs are formed as well." (PMID 27483250, 2016).
intervertebral disc degeneration (14 papers, 2012 to 2025). "The downstream target of miR-31-5p is matrix metalloproteinase-3 (MMP3), and its downregulation can promote the degradation of the extracellular matrix and lead to intervertebral disk degeneration." (PMID 39440032, 2024). "Previously we indicated that TWEAK is involved in intervertebral disc degeneration by inhibiting the production of cartilage matrix in the intervertebral disc, and inducing the further expression of MMP‐3." (PMID 32211586, 2020). "In vitro studies have also highlighted the role of MMP3 in intervertebral disc degeneration through matrix degradation." (PMID 23522322, 2013). "Furthermore, functional assays revealed that 17β-Estradiol suppresses intervertebral disc degeneration via decreasing MMP3 level and increasing Collagen-II expression in a rat model." (PMID 35100096, 2022). "For example, MMP3 has been reported as a key gene in maintaining homeostasis of the extracellular matrix, and in vivo study showed that gene therapy targeting MMP3 was an efficient way to delay intervertebral disc degeneration." (PMID 32873329, 2020). "The MMP family is instrumental during extracellular matrix metabolism, and MMP3, as a member of MMP family, is involved in the progression of intervertebral disc degeneration." (PMID 35100096, 2022). "A dominant imbalance of MMP-3/TIMP-1 and TIMP-2 relative to ADAMTS-4 and ADAMTS-5/TIMP-3 signifies an advanced stage of intervertebral disc degeneration." (PMID 22394620, 2012). "A dominant imbalance of MMP-3/TIMP-1 and TIMP-2 relative to ADAMTS-4 and ADAMTS-5/TIMP-3 is a possible indication of an advanced, irreversible stage of intervertebral disc degeneration." (PMID 22394620, 2012). "Integrated with these reports, our findings show that a state of dominant MMP-3/TIMP-1 and TIMP-2 imbalance relative to ADAMTS-4 and ADAMTS-5/TIMP-3 imbalance may indicate an irreversible stage of intervertebral disc degeneration." (PMID 22394620, 2012). "Furthermore, it was reported that UTI effectively inhibited the increased expression of MMP-2, MMP-3, NOS in degenerated NP cells induced by IL-1β in vitro which suggests that UTI may potentially be useful for clinical therapy of intervertebral disc degeneration." (PMID 27638499, 2016).
liver fibrosis (14 papers, 2015 to 2025). "A positive correlation between higher MMP-3 levels, and presence of specific AMA type M2 autoantibodies and increased bilirubin concentration suggests that MMP-3 can be associated with a rapidly evolving disease of the liver, including hepatic fibrosis in PBC patients." (PMID 35529854, 2022). "Higher MMP-3 activity in pathological conditions may be associated with liver fibrosis through the cell-matrix interaction mechanism." (PMID 35529854, 2022). "The level of MMP-3 was associated with hepatic dysfunction and could play a role in the pathophysiology of hepatic fibrosis in PBC." (PMID 35529854, 2022). "Generation of C-terminal AAT peptides, such as C37 and C42, depends on specific matrix metalloproteinases (MMPs), which contribute to liver fibrosis; for example, MMP-3 is altered in children with AATD, and MMP-7 is upregulated in pediatric biliary atresia." (PMID 41450890, 2025). "As compared to the control animals, the group treated with methotrexate alone had shown strong evidence of hepatic fibrosis as proven by the significant increase in the hepatic tissue content of hydroxyproline, MMP-3, and MMP-9." (PMID 40143135, 2025). "The concentration of MMP-3 in sera of PBC patients was also found to correlate with the state of liver fibrosis (OR = 4.3; p < 0.01)." (PMID 35529854, 2022). "Increased MMP-3 concentrations were positively correlated with various clinical and immunological parameters, and advanced liver fibrosis." (PMID 35529854, 2022). "The serum MMP-3 concentrations were significantly correlated with the degree of liver fibrosis (r = 0.5, p<0.0001)." (PMID 35529854, 2022). "MMP3 encodes a matrix metalloproteinase, which is known to play a critical role in maintaining extracellular matrix (ECM) homeostasis by breaking down MMP3-sensitive ECM components in physiological and pathological processes, such as liver fibrosis." (PMID 37603094, 2023). "Perhaps a similar scenario may occur in the case of liver fibrosis, as elevated levels of MMP-3 were found in the sera of these patients." (PMID 35529854, 2022). "Liver fibrosis monitored by the accumulation of α-Sma, collagen I, desmin, and Sirius red staining, as well as by measuring the mRNA levels of α-Sma, Col1a1, Mmp-3, and Tgfβ1, was significantly decreased by KY19334 treatment compared to treatment with selonsertib or ocaliva." (PMID 36114279, 2022). "Our results may suggest that a high serum concentration of MMP-3 can be related to the degree of liver fibrosis." (PMID 35529854, 2022). "Our aim in the present study was to determine whether the measurement of serum MMP-3 is clinically useful for assessing ongoing liver fibrosis in patients with PBC." (PMID 35529854, 2022). "However, Mmp3 and Timp1 genes, whose impact on liver fibrosis is controversial or unclear, were strongly induced in wildtype mice livers but showed significantly lower or negligible induction in NLRC5-deficient livers." (PMID 34712238, 2021). "Based on results of network pharmacology, it was known that flavonoids can possibly suppress liver fibrosis by inhibiting the IL-17 signaling pathway, which includes NF-κB, AP-1, IL-6, IL-1β, TNFα, IFN-γ, CCL2, COX2, MMP1, MMP3, and MMP9." (PMID 33551818, 2020). "Previous studies have shown that FIS supplementation prevents hepatic fibrosis by suppressing the gene expressions of COL1, MMP2, MMP3, and MMP9 and collagen accumulation." (PMID 33381023, 2020). "Additionally, MMP2, MMP3, and MMP9 are highly expressed during the acute phase of tissue damage, and the role of MMP12 in the treatment of mesenchymal stem cells for liver fibrosis has been reported." (PMID 37189708, 2023). "Liver fibrosis was mostly not observed, as shown by the histological analyses with reduced mRNA levels of fibrogenic markers, including alpha smooth muscle actin (α-Sma), collagen type 1 alpha 1 (Col1a1), metalloprotein-3 (Mmp-3), and transforming growth factor beta (Tgfβ)." (PMID 36114279, 2022).
liver fibrosis (continued). "The reason for the increased activity of MMP-3 and the relationship of MMP-3 to liver fibrosis is not entirely clear." (PMID 35529854, 2022).